ATF1 (activating transcription factor 1)
Diseases named in the same sentence as ATF1 in open-access papers (continued):
Sharing a sentence is not in itself a finding about the gene and the disease.
infection (5 papers, 2016 to 2025). The state of being infected such as from the introduction of a foreign agent such as serum, vaccine, antigenic substance or organism. "One transcription factor that was predicted to bind to the HCLS1 promoter was ATF1, and this particularly came to our attention because it is known to be upregulated by Src signaling, a signaling pathway known to be involved in infection of monocytes by HCMV." (PMID 31569051, 2019). "We now compared the gene sets differentially expressed in the SGE1, aTF1 and cTF1 overexpressors and during infection." (PMID 27855160, 2016). "Given that expression levels of SGE1, aTF1 and cTF1 increase during infection, we assume that strains overexpressing either of these transcription factor genes partially mimic the in planta state." (PMID 27855160, 2016). "Only the aTf1 and the Sge1 DNA binding sites were significantly enriched among up-regulated genes, and none of the DNA binding sites was enriched among genes down-regulated during infection." (PMID 27855160, 2016). "Accordingly, we demonstrate that upon ATF1 KO, levels of CCR5-AS and CCR5 expression are also diminished, and this further inhibits infection of an R5 tropic HIV." (PMID 40607797, 2025). "Both aTf1 and cTf1 up-regulate expression of the shorter aTF1 gene on the pathogenicity chromosome (FOXG_16414), although not to the same level as during infection." (PMID 27855160, 2016).
adenocarcinoma (2 papers, 2013 to 2018). A common cancer characterized by the presence of malignant glandular cells. "The modest roles of CREB and, by implication, CREM and ATF1 in the GI was a genuine surprise, but there was evidence that pCREB/CREM/ATF1 is elevated in early-stage and advanced adenocarcinoma in the mouse." (PMID 23618903, 2013).
ATF1 also shares sentences with these, for which no sentence is quoted: myxoid liposarcoma (6 papers); alveolar rhabdomyosarcoma (4); synovial sarcoma (4); salivary gland tumors (3); cutaneous melanoma (2); digestive system tumors (2); essential hypertension (2); metastatic melanoma (2); myxoid chondrosarcoma (2); non-small cell lung carcinoma (2); pleural mesothelioma (2); acute leukemia (1); bone cyst (1); breast adenocarcinoma (1); coronary heart disease (1); dermatofibrosarcoma protuberans (1); enteritis (1); epithelial carcinoma (1); epithelial-myoepithelial carcinoma (1); epithelioid hemangioendothelioma (1); esophageal squamous cell carcinoma (1); glioma (1); hemangioma (1); hemorrhage (1); intracranial hemorrhage (1); lymph node metastasis (1); meningioma (1); myoepithelial carcinoma (1); neuroepithelial tumor (1); NUT carcinomas (1).
A further 11 diseases each share a sentence with ATF1 in 1 paper.